ZNF521 (zinc finger protein 521)
Diseases named in the same sentence as ZNF521 in open-access papers (continued):
Sharing a sentence is not in itself a finding about the gene and the disease.
ovarian carcinoma (6 papers, 2021 to 2024). A malignant neoplasm originating from the surface ovarian epithelium. "ZNF521 is expressed in ovary and ovarian cancers and mutations of its gene (almost invariably amplifications) are present in >6% of OCs." (PMID 36191006, 2022). "Taken together the analyses of different public genomic databases indicate that ZNF521 is: i) amplified in 6% of ovarian carcinoma cases and ii) associated to poor survival in ovarian cancer patients." (PMID 36191006, 2022). "Additionally, in ovarian cancer an integration analysis of microRNA and mRNA gave a positive association of ZNF521 with the miR34-family and miR133b." (PMID 36191006, 2022). "In exosomes derived from Bone Marrow Stromal Cells (BMSCs), ZNF521 was identified as hub protein and associated with poor outcome in gastric and ovarian cancers where OCSC are shown to be implicated in the progression of ovarian carcinoma and resistance to therapy." (PMID 36191006, 2022). "The aberrant expression of ZNF521 transcripts, frequently associated with miRNA deregulation, has been detected in several tumors including pancreatic, hepatocellular, gastric, bladder transitional cell carcinomas as well as in breast and ovarian cancers." (PMID 34445164, 2021). "In this study the role of ZNF521 is investigated in the regulation of human ovarian carcinoma cells." (PMID 36191006, 2022). "Overall, we found that higher levels of ZNF521 in HeyA8 and ES-2 human ovarian cancer cell lines enhances their growth, ability to migrate and to form OC spheroids." (PMID 36191006, 2022). "A significant number of gene amplifications for ZNF521 are detected in ovarian cancers (~6%)." (PMID 36191006, 2022). "ZNF521 regulates proliferation, progression and CSC (cancer stem cell) compartments in human ovarian cancer (hOC), which is a very aggressive and late-diagnosed female tumor." (PMID 37834202, 2023).
acute myeloid leukemia (4 papers, 2016 to 2023). Acute myeloid leukemia (AML) is a group of neoplasms arising from precursor cells committed to the myeloid cell-line differentiation. "Interestingly, our data demonstrate that HOXB5 and ZNF521 are co-expressed in myeloid progenitors, while others have reported their aberrant expression in corresponding acute myeloid leukemia." (PMID 37371852, 2023). "In humans ZNF521 over‐expression is found in acute myeloid leukemia but not in B‐cell leukemia, although B‐cell leukemia initiating cells do show increased expression of ZNF521." (PMID 27506447, 2016).
acute lymphoblastic leukemia (3 papers, 2011 to 2016). Leukemia with an acute onset, characterized by the presence of lymphoblasts in the bone marrow and the peripheral blood. "One of these rearrangements had a breakpoint in a gene, ZNF521, which was recently identified as the subject of chromosomal translocations in acute lymphoblastic leukaemia." (PMID 21750719, 2011). "Furthermore, ZNF521 is expressed in human hematopoietic cells, and translocations between ZNF521 and PAX5 are associated with pediatric acute lymphoblastic leukemia." (PMID 27506447, 2016).
B-cell lymphomas (3 papers, 2015 to 2023). "Comparative gene expression profiling analysis of SC-1 versus seven B-cell lymphoma control cell lines demonstrated elevated HOXB5 activity and revealed high expression levels of ZNF521 in SC-1." (PMID 37371852, 2023). "We have shown that ZNF521 activates HOXB5 expression, supporting a potential stem cell role oncogenically reactivated by HOXB5 in B-cell lymphoma." (PMID 37371852, 2023).
bladder cancer (2 papers, 2021 to 2022). "ZNF521 expression is influenced by miRNAs also in urological malignancies, including bladder cancer (BC)." (PMID 34445164, 2021). "ZNF521, together with TMCC1, TNIP1, VSTM2B, ISL1, emerged as target genes of miR-517a, the expression of which is significantly enhanced in bladder cancer." (PMID 34445164, 2021).
breast carcinoma (2 papers, 2020 to 2024). "BCL11A, MLLT3, ZNF521, PHC1, and PCGF3 also showed subtype-specific dysregulation in breast cancers; BCL11A, ZNF521, and PHC1 were specifically downregulated in luminal subtype cancers relative to their matched normal tissue." (PMID 39545637, 2024).
chronic lymphocytic leukemia (2 papers, 2020 to 2023). "Next to the oncogenic potential of MLL rearrangement via ZNF521 or EVI1, which enhances AML transformation, NOTCH1 upregulation is known to be particularly relevant in lymphoid leukemia such as T-ALL or chronic lymphocytic leukemia (CLL) and is associated with a poor prognosis." (PMID 37833915, 2023).
colorectal cancer (2 papers, 2016 to 2025). A primary or metastatic malignant neoplasm that affects the colon or rectum. "ZNF521 encodes a transcriptional co-repressor involved in chromatin remodeling and has been implicated in the pathogenesis of breast, lung, and colorectal cancers through its role in genomic instability." (PMID 40486961, 2025).
myeloid leukemia (2 papers, 2021 to 2024). A clonal proliferation of myeloid cells and their precursors in the bone marrow, peripheral blood, and spleen. "ZNF521 is expressed in some cancers such as myeloid leukemia, in which it is tagged as a potential therapeutic pathway because of its role in DNA transcription." (PMID 39025327, 2024).
colorectal tumors (1 paper, 2024). "Nonetheless, we observed some nominally significant differential associations in 12 genes, including positive associations between folate intake and the risk of CHD1-, DOCK3-, and ZNF521-mutated colorectal tumors, which warrant replication in future studies." (PMID 39025327, 2024).
endometriosis (1 paper, 2021). The growth of functional endometrial tissue in anatomic sites outside the uterine body. "In ovarian endometriosis ZNF521 appears also in a complex integrated miRNA–TF–gene regulatory network, it is possible that a deregulation in the relationship between ZNF521 and ovarian tissue-specific miRNAs could induce molecular changes causing endometriosis." (PMID 34445164, 2021).
idiopathic pulmonary fibrosis (1 paper, 2021). Idiopathic pulmonary fibrosis (IPF) is a nonneoplastic pulmonary disease that is characterized by the formation of scar tissue within the lungs in the absence of any known cause. "ZNF521 is differentially expressed in IPF and can be deregulated by specific miRNAs (hsa –mir-19b-3p, hsa -mir-30a-5p, hsa -mir-30d-3p, hsa -mir-92a-3p), which have been recently identified as regulators for genes in pulmonary fibrosis." (PMID 34445164, 2021).
insomnia (1 paper, 2024). A sleep disorder characterized by difficulty in falling asleep and/or remaining asleep. "In the realm of sleep and circadian health, reported genetic associations corroborated the relevance of EFNA5, ZNF521, WWOX, ALG10B, PAM and SDK1 with insomnia, daytime napping, or chronotype traits." (PMID 39070651, 2024).
Insulin resistance (1 paper, 2019). Increased resistance towards insulin, that is, diminished effectiveness of insulin in reducing blood glucose levels. "ZNF521 mRNA also correlated positively with degree of insulin resistance in FDR as a marker of their reduced SAT adipogenesis and expanded adipose cells." (PMID 31227697, 2019).
Obesity (1 paper, 2022). Accumulation of substantial excess body fat. "Although recent studies suggested that the inhibitory effect of ZNF521 is not sufficient for impaired adipogenesis and development of the unhealthy metabolic state in obesity, its repression is necessary for proceeding adipocyte differentiation." (PMID 35397570, 2022).
pulpitis (1 paper, 2025). Inflammation of the dental pulp. "The discovery GWAS also identified several other associated loci, including three in chromosomes 6 (near IBTK), 14 (near NOVA1), and 18 (near ZNF521) shared by the phenotypes Pulpitis and Pulpal and apical diseases." (PMID 40701953, 2025).
schizophrenia (1 paper, 2021). A major psychotic disorder characterized by abnormalities in the perception or expression of reality. "According to the pathological manifestations and the level of neurotransmitters in the brain, deficiency of ZNF521 can lead to manifestations associated with schizophrenia." (PMID 34867169, 2021). "The results of the behavior test suggested that ZNF521–/– mice have a hyper-locomotive phenotype which is a classical feature of rodent models of schizophrenia and corresponds to the clinical symptoms of patients with schizophrenia." (PMID 34867169, 2021). "C2H2 type subfamily plays an important role in schizophrenia including ZNF521 and ZEB2." (PMID 34867169, 2021).
serous ovarian cancers (1 paper, 2022). "Profiling of 157 advanced stage serous ovarian cancers, ZNF521 (known regulator of the homeostasis in stem cells compartment and in cancer) results in a set of 86-genes with significant poor overall survival profiles." (PMID 36191006, 2022).
serous ovarian cystadenocarcinomas (1 paper, 2022). "Moreover, recently, ZNF521 was identified as one of the top 15 genes significantly correlated with the overall survival in 1692 serous ovarian cystadenocarcinomas." (PMID 36191006, 2022).
Waldenstrom macroglobulinemia (1 paper, 2019). "Besides, some genes are involved in osteoblastogenesis (SEMA3A, BICC1, CHRLD1, and ZNF521) and HAS1 is involved in Waldenstrom’s macroglobulinemia, a post-follicular B-cell lymphoproliferative disorder also associated with M-protein production (IgM)." (PMID 30705326, 2019).
tumor (17 papers, 2013 to 2025). "ZNF521 exhibits chromosomal rearrangement or loss in 63% PDAC tumours and an overall trend of reduced expression in PDAC tumours compared with matched normal ductal epithelial cells." (PMID 35061935, 2022). "Zinc finger protein 521 (ZNF521) encodes a transcription factor with a zinc finger domain that is widely expressed in many tissues and plays important roles in tumor formation and development." (PMID 36311294, 2022). "In clinical data, we showed that down-regulated ZNF521 was significantly associated with large tumor size and advanced TNM stage." (PMID 32913476, 2020). "The down-regulated ZNF521 was significantly associated with large tumor size (P = 0.026) and advanced TNM stage (P = 0.018)." (PMID 32913476, 2020). "More importantly, knockdown of ZNF521 failed to inhibit GC progression in the presence of AKR1B1 overexpression, demonstrating that AKR1B1 is essential in the ZNF521‐mediated tumor‐promoting activity of ZNF521." (PMID 36397644, 2023). "Analysis of RNA isolated from transduced cells by RNA-Seq and qRT-PCR revealed that several genes involved in growth, proliferation, migration and tumor invasiveness are differentially expressed following increased ZNF521 expression." (PMID 36191006, 2022). "We next analyzed the relationship between ZNF521 expression and immune infiltration levels in 39 tumor types using the TIMER database." (PMID 36311294, 2022). "We focused on ZNF521 expression and its relationship with clinicopathological features and prognosis to reveal the relationship between ZNF521 and tumor immune infiltration." (PMID 36311294, 2022). "ZNF521 was primarily localized within the cytoplasm of cancer cells, and ZNF521 expression in non-tumor mucosa was also recorded." (PMID 36311294, 2022). "miR-802 overexpression significantly reduced the transcription factor expression in HCC cells with wild-type ZNF521 3′UTR compared to non-tumor tissues; on the other hand, anti-miR-802 induced an increase in ZNF521 mRNA and protein in HCC." (PMID 34445164, 2021). "Further accumulation of mutations in ZNF521, TRRAP, and RBFOX1 result in the metastatic clade that forms the third subclone (marked in red), and mark the point of tumor dissemination to the liver." (PMID 34149820, 2021). "Down-regulated ZNF521 expression was significantly associated with malignant prognostic features, including advanced TNM stage and large tumor size." (PMID 32913476, 2020). "To further explore the function of ZNF521 on tumor growth in vivo, we used the subcutaneous tumor model and the data showed that ZNF521 overexpression significantly inhibited the tumor growth than control cells in mice (P < 0.05)." (PMID 32913476, 2020). "Although all genes were downregulated in tumor samples when compared with normal controls, we only found a statistically significant difference for the ZNF521 gene (p = 0.046)." (PMID 30705326, 2019). "Additionally, ZNF521 expression was associated with GC TNM stage, tumor size, and local lymph node metastasis." (PMID 36397644, 2023). "Recently, we identified the multi-zinc finger protein ZNF521 as a regulator of tumor growth, proliferation and migration in hEOC (human epithelial ovarian carcinoma) through the modulation that ZNF521 exerts on key regulatory genes involved in EMT (epithelial mesenchymal transition)." (PMID 37834202, 2023). "Our data, for the first time, identified the modulatory function that ZNF521 exerts on the NRF2-NOTCH axis in this tumor model, and whose expression could be used to select hOC patients potentially responsive to treatments with NRF2 or NOTCH inhibitors." (PMID 37834202, 2023). "We analyzed ZNF521 expression in normal and tumor tissues by IHC." (PMID 36311294, 2022). "Indeed, whole-transcriptome profiling of OC cell lines confirmed the profound transcriptional impact of ZNF521 expression modulation on a set of genes involved in tumour growth, proliferation, migration and metastasis." (PMID 36191006, 2022).
tumor (continued). "ZNF521 has consistently lower expression in all the samples from tumours P8–P19, except P9–T4." (PMID 35061935, 2022). "Consistently, we found that ZNF521 was lowly expressed in all the samples from tumours P8–P19, except P9–T4, suggesting that low expression of ZNF521 may serve as a biomarker for PDAC." (PMID 35061935, 2022). "Moreover, we analyzed the correlation between ZNF521 expression and infiltrating immune cells in different tumor microenvironments through the tumor immune database TIMER." (PMID 36311294, 2022). "The integrated multi‐omics analysis revealed that despite the heterogeneities observed in certain omics, low expression of ZNF521 and loss of KDM6A copy number were consistently presented within and across individual tumours, serving as potential biomarkers for PDAC." (PMID 35061935, 2022). "Down-regulated ZNF521 expression may be relevant as a prognostic factor in malignant HCC, especially in the tumor TNM stage that is associated with poor prognosis." (PMID 34445164, 2021). "Zinc finger protein 521 (ZNF521) plays an important role in the tumor development and process." (PMID 32913476, 2020). "Therefore, we demonstrated that ZNF521 plays a role as a tumor suppressor in HCC progression." (PMID 32913476, 2020). "Furthermore, expression of four proteins is associated with tumor progression/high risk AML: DOT1L, mTOR, VIM and ZNF521, whereas the expression of six proteins is associated with tumor suppression/low risk AML: AEBP2, CAST, CBFB, LSP1, MAP1S and probably PCBP1." (PMID 30634713, 2019). "For example, the nucleotide at chr18: 22806878 of ZNF521 of hg19 is C; but two peaks (C and T) of approximately equal peak height were seen in sequence of normal lung tissues, whereas a high peak of C and a low peak of T were detected in tumor samples of the patient." (PMID 29262625, 2017). "By binding with EBF1, ZNF521 antagonized its transcription repressor function on the expression of AKR1B1, liberating the tumor‐promoting activity of AKR1B1." (PMID 36397644, 2023). "The findings of this report elucidate the important role of ZNF521 in stomach adenocarcinoma (STAD) and suggest a potential relationship and mechanistic link between ZNF521 and tumor immune interaction." (PMID 36311294, 2022). "The results revealed that ZNF521 mRNA and protein was robustly reduced in HCC tissues relative to that in adjacent non-tumor tissues (P < 0.05)." (PMID 32913476, 2020). "In addition, it was shown in HCC cells that ZNF521, acting as a co-transcriptional repressor, binding Runx2 and inhibiting its transcriptional activity involving PI3K/AKT signaling, blocks the tumor progression." (PMID 34445164, 2021). "However, the study also revealed that elevated levels of another transcription factor, zinc finger protein 521 (ZNF521), in tumor tissues could indirectly promote AKR1B1 expression by suppressing EBF1." (PMID 40508012, 2025).